IL1A (interleukin 1 alpha)
Diseases named in the same sentence as IL1A in open-access papers (continued):
Sharing a sentence is not in itself a finding about the gene and the disease.
Crohn disease (9 papers, 2018 to 2025). A gastrointestinal disorder characterized by chronic inflammation involving all layers of the intestinal wall, noncaseating granulomas affecting the intestinal wall and regional lymph nodes, and transmural fibrosis. "Notably, researchers have found that IL-1α/IL-1β and IL-10 are critical regulators of monocyte IL-23 production, distinguishing homeostatic IL-23 production from inflammation-associated IL-23 production in patients with severe ulcerative active Crohn’s disease." (PMID 40564117, 2025). "Expression of pro-inflammatory cytokines: IL-1α, IL-1β, TNFα, and IL-15 were increased in IL-1rn-/- mice, and these results are in agreement with those obtained from patients with Crohn's disease." (PMID 31191826, 2019). "A preclinical study demonstrated that neutralizing IL-1α reduced disease severity (IL-1α is a potent activator of fibroblast) in a mouse model of Crohn’s disease via modulation of the gut microbiome and correction of mucosal dysbiosis, suggesting potential therapeutic benefits." (PMID 40869366, 2025). "In a Crohn’s disease model, CXCL10 blockade reduces serum IL-12p40, IL-2, IFN-γ, IL-1α, IL-1β, and TNF-α." (PMID 29910805, 2018). "In another study in a murine model of Crohn's disease, UCN could control inflammatory diseases by inhibiting a wide range of inflammatory cytokines such as TNF-α, IFN‐γ, IL-6, IL-1α, IL-1β, IL-12, IL-18, IL-17, and IL-15." (PMID 35419072, 2022). "In recent studies targeting Crohn’s disease in humans, it was evidenced that the kinase MAP3K4 (Mitogen-activated protein kinase 4) was responsible for variation of IL1A, regardless of variation in TLR activation." (PMID 30161141, 2018).
cryopyrin-associated periodic syndrome (9 papers, 2020 to 2025). Cryopyrin associated periodic syndrome (CAPS) defines a group of autoinflammatory diseases, characterized by recurrent episodes of systemic inflammatory attacks in the absence of infection or autoimmune disease. "Anakinra, a recombinant IL-1 receptor antagonist, blocks the interaction of IL-1β and IL-1α with its receptor and is indicated for RA and cryopyrin-associated periodic syndromes (CAPS)." (PMID 35214755, 2022). "Anakinra is a recombinant form of human IL-1R antagonist, which blocks the signal transduction of both IL-1α and IL-1β and has been approved to treat active RA and cryopyrin-associated periodic syndromes (CAPS)." (PMID 33816637, 2021). "IL-1Ra inhibits the activity of both IL-1α and IL-1β and is clinically approved as the drug anakinra for treating autoimmune disorders such as cryopyrin-associated periodic syndrome (CAPS), Still’s disease, familial Mediterranean fever (FMF), rheumatoid arthritis, and periodic fever syndromes." (PMID 41301455, 2025). "Anakinra is a recombinant human IL-1Ra that competitively inhibits IL-1α and IL-1β interaction with IL-1R1 and is currently indicated for the treatment of refractory RA and for CAPS (Cryopyrin Associated Periodic Syndrome)." (PMID 37849737, 2023). "The extracellular portion has a strong affinity for both IL-1α and IL-1β, thereby neutralising their activities and functioning as an “IL-1 trap”.127,128 It was approved by the FDA in 2008 for the treatment of cryopyrin-associated periodic syndromes (CAPS)." (PMID 31900383, 2020).
diabetic nephropathy (9 papers, 2020 to 2025). "People with diabetic nephropathy have elevated levels of both IL‐1β and IL‐1α in their serum, with a recombinant human IL‐1 receptor antagonist (BLG‐553902) demonstrating efficacy in abrogating accumulation and deposition of fibrotic markers in PTECs." (PMID 38995865, 2025). "Another clinical study in the same year suggested that after 11 days of DQ in patients with diabetic nephropathy, the expression of p16INK4A by senescent adipocytes was reduced and SASP levels (e.g., IL-6, IL-1α) were also decreased." (PMID 35897741, 2022).
endothelial dysfunction (9 papers, 2015 to 2024). In vascular diseases, endothelial dysfunction is a systemic pathological state of the endothelium (the inner lining of blood vessels) and can be broadly defined as an imbalance between vasodilating and vasoconstricting substances produced by (or acting on) the endothelium. "The ABIN(D485N) mice display endothelial dysfunction and cardiac hypertrophy, which is possibly mediated through IL-6 and, to a lesser degree, IL-1α." (PMID 25648164, 2015). "This process activates these immune cells and induces the release of additional pro-inflammatory cytokines, i.e., IL1α, IL1β, TNFα, IFNγ, and IL17, which may exacerbate endothelial dysfunction and contribute to the degradation of the endothelial glycocalyx." (PMID 39596318, 2024). "Taken together, the increased levels of IL-1α, IL-6, and TNF-α in MSK1/2 KO mice could explain the observed endothelial-dysfunction in this study, although the mechanisms of diminished NO bioavailability may be multi-modal and requires further scrutiny." (PMID 34445361, 2021).
Granuloma (9 papers, 2013 to 2025). A compact, organized collection of mature mononuclear phagocytes, which may be but is not necessarily accompanied by accessory features such as necrosis. "Indeed, we observed that the elevated number of cells, presented in IL-1α-deficient mice after 15 and 30 dpi, was arranged in organized and well-formed granulomas." (PMID 31425553, 2019). "The number of macrophages producing IL-1α and GM-CSF was increased in Gran/2 granulomas as compared with Gran/1 granulomas (&P < 0.05 and **P < 0.01, resp)." (PMID 24198843, 2013). "TNF-α and IL-1α are the predominant contributors of granuloma formation." (PMID 38481606, 2023). "Similarly, our present observations indicated that higher expression levels of both IL-1α and IL-1β were found in the granuloma group compared to those in cyst and control groups." (PMID 30012121, 2018). "Inflammatory mediators such as interleukin-1α (IL-1α), TNF-α and IL-6 are recognized to be involved in the formation of the granuloma." (PMID 30917586, 2019). "Interestingly, mice singly deficient for IL-1α or for IL-1β developed some granuloma with limited oedema, no necrosis and free alveolar space, thus a much less severe lung pathology than that seen in the absence of both IL-1α and IL-1β or of IL-1R1 at 5 weeks post-infection." (PMID 25400917, 2013). "However, caspase-11 does not seem to be important for this process, suggesting that the caspase-11/IL-1α axis is not critical for the structural formation of granulomas in this context." (PMID 31425553, 2019). "Indeed, we recently showed that mice lacking IL-1β, IL-1α or IL-1R and treated with DQ12 silica presented a reduction of chronic lung inflammation and granuloma formation compared to their WT counterparts." (PMID 25497724, 2014).
head and neck cancer (9 papers, 2013 to 2025). A primary or metastatic malignant neoplasm affecting the head and neck. "In advanced NSCLC, high IL-1β levels were identified as an adverse prognostic factor associated with shorter progression-free and OS, while in head and neck cancer elevated IL-1α correlated with an increased risk of distant metastasis." (PMID 41465261, 2025). "Interleukin-1 alpha (IL1A) plays a significant role in head and neck cancer by primarily acting through the NF-κB signaling pathway." (PMID 39065771, 2024). "The same histopathologic results were observed in head and neck cancer, where higher expression of interleukin 1-A (encoded by IL1A gene, alias IL-1A) is associated with metastasis and the worst outcome." (PMID 37763742, 2023). "Previous studies have shown the tumor-promoting function of inflammatory cytokine IL-1α in multiple cancer models, such as for liver, lung, ovarian, pancreatic, and head and neck cancers." (PMID 37835389, 2023). "In addition, inactivation of NF-κB in HNSCC suppressed cell survival and expression of IL-1α, IL-6, CXCL8 and GM-CSF in a murine model of head and neck cancer and its aberrant expression is associated with poor prognosis in solid cancers." (PMID 35048046, 2021). "In order to comprehensively recognize the role and potential mechanism of the COL1A1, IL1A, MMP9, and FN1 genes in the prognosis of head and neck cancer, we constructed a miRNA-related regulatory network in the current study." (PMID 39065771, 2024). "Our data have also shown increased mRNA level of pro-inflammatory cytokines such as Il1a, Il1b, Tnf, Ptgs2 in mouse ASCC as compared with control anal skin, which is well demonstrated in human and mice head and neck cancer." (PMID 24124460, 2013).
multiple sclerosis (9 papers, 2011 to 2025). A progressive autoimmune disorder affecting the central nervous system resulting in demyelination. "NF-κB activation in turn upregulates the expression of several genes implicated in the pathogenesis of multiple sclerosis, such as TNFα, iNos and IL1α/IL1β." (PMID 37999377, 2023). "Of interest, IFNβ and glatiramer acetate, disease-modifying treatments for multiple sclerosis, are both known to exert opposing effects on IL-1α/β and IL-1ra." (PMID 22208359, 2011).
pericarditis (9 papers, 2021 to 2025). An inflammatory process affecting the pericardium. "The pathogenic role of IL-1 family members such as IL-1α, IL-1β, and IL-33 in pericarditis has been studied clinically and preclinically." (PMID 35251049, 2022). "In 2021, the results on the efficacy and safety of rilonacept, an IL-1α and IL-1β cytokine trap in patients with recurrent pericarditis (≥2 recurrences), were published." (PMID 38541631, 2024). "The therapeutic use of IL-1α and IL-1β inhibitors in patients with pericarditis has improved pain and inflammation in clinical trials." (PMID 35251049, 2022). "Rilonacept, a soluble IL-1 receptor chimeric fusion protein neutralizing interleukin 1 alpha (IL-1α) and interleukin 1 beta (IL-1β), has demonstrated promising results in a phase II study in recurrent or refractory pericarditis." (PMID 36505131, 2022). "Moreover, they demonstrated increased expression of IL-1α and IL-1β in the pericardium of mouse models of pericarditis compared with controls." (PMID 41272654, 2025). "Adding to this momentum, Kiniksa Pharmaceuticals is advancing the development of KPL-387, a fully human immunoglobulin G2 (IgG2) monoclonal antibody that targets IL-1R type 1, thereby inhibiting the activity of both IL-1α and IL-1β, key drivers of inflammation in recurrent pericarditis." (PMID 41136179, 2025). "Inhibition of both IL-1α and 1β seems crucial to abate inflammation in acute pericarditis." (PMID 38541631, 2024). "Impact of recurrent pericarditis (RP) on patient health-related quality of life (HRQoL) was evaluated through qualitative patient interviews and as an exploratory endpoint in a Phase 2 trial evaluating the efficacy and safety of rilonacept (IL-1α/IL-1β cytokine trap) to treat RP." (PMID 33882846, 2021). "Approved in 2008, rilonacept effectively neutralizes IL-1α and IL-1β, showing distinctive efficacy in treating CAPS and recurrent pericarditis." (PMID 41471316, 2025).
steatosis (9 papers, 2014 to 2025). Increased lipid within the cytoplasm of cells. "IL1α was reported to be ~122% and ~300% higher in patients with steatosis and steatohepatitis than in controls." (PMID 35405942, 2022). "Portal macrophages are detectable in steatosis alone as the earliest change, followed by an elevated expression of pro-inflammatory cytokines such as IL-1α and TNF-alpha in early NASH." (PMID 33202693, 2020). "However, studies using IL-1α and IL- 1β knockout mice showed improved diet-induced steatosis, indicating that both IL-1α and IL- 1β contribute to NASH development." (PMID 39995661, 2025). "Additionally, IL-1β KO mice are protected from diet-induced steatosis, whereas IL-1α KO mice develop steatosis." (PMID 25216251, 2014). "While IL-1α and IL-1β play a pivotal role in inflammation and inflammatory diseases, including hepatic steatosis, other members of this family may hold anti-inflammatory or pro-inflammatory functions during liver inflammation and steatosis." (PMID 27942420, 2016). "Several studies have shown that IL1α is increased in NASH/NAFLD patients and is positively correlated with advanced stages of steatosis and steatohepatitis." (PMID 35405942, 2022). "Previous studies have reported that eotaxin-2/CCL24, IL-1α, IL-12, and TNF-α, respectively, are the important mediators in the steatosis model." (PMID 25799095, 2015). "In this study, eotaxin-2/CCL24, IL-1α, IL-12, and TNF-α production in mice treated with CCl4 was increased compared with that in control mice, suggesting these cytokines and chemokines play a critical role in CCl4-induced steatosis." (PMID 25799095, 2015).
thyroid cancer (9 papers, 2014 to 2025). "Studies have shown that IL1A gene polymorphisms (e.g., rs3783521, rs3783546) are significantly associated with thyroid carcinoma risk, particularly in male patients." (PMID 40823082, 2025). "IL1B polymorphisms were associated with an increased thyroid cancer risk after the fifth decade of life (>48 years old), whereas IL1A polymorphisms and thyroid cancer susceptibility were linked to age below this threshold." (PMID 37189693, 2023). "A link between thyroid cancer and inflammation has also been recognized; thyroid carcinomas are associated with the constitutive expression of several proinflammatory cytokines (IL-8, IL-6, GROα, IL-1α, G-CSF, GM-CSF) that can be able to maintain the invasive phenotype." (PMID 25268744, 2014). "IL-1α and IL-1β, encoded by the IL1A and IL1B genes, promote inflammatory responses and tumor progression in thyroid carcinoma." (PMID 40823082, 2025). "Twelve SNPs of IL1A and IL1B were examined, concluding that six of them (rs3783521, rs3783546, rs3783550, and rs1609682 for IL1A and rs3136558 and rs1143623 for IL1B) were linked to an increased susceptibility to thyroid cancer development." (PMID 37189693, 2023). "In thyroid cancer, CREB3L1 mediates IL‐1α production to activate α‐SMA‐positive fibroblasts and downstream ECM signalling." (PMID 39902627, 2025). "Studies have shown that α-SMA-positive CAFs were activated through CREB3L1-mediated IL-1α production, the presence of CAF inhibits thyroid cancer growth and metastasis after CREB3L1 knockdown." (PMID 37719863, 2023). "Tumor-related leukocytosis caused by the release of cytokines such as granulocyte colony-stimulating factor (g-csf), granulocyte-macrophage colony-stimulating factor (gm-CSF), IL-1a,b, IL-3, IL-6, and TNF-α and its prognostic effect have been described in various cancers, including thyroid cancers." (PMID 40004836, 2025).
chorioamnionitis (8 papers, 2006 to 2025). A morphologic finding indicating inflammation of the fetal sac membranes. "Our analysis included inflammatory mediators reported to be associated with chorioamnionitis, preterm labor, and fetal inflammatory response syndrome such as IL-1α, IL-1β, IL-6, TNF-α, S100A8, and S100A9." (PMID 22952869, 2012). "Intraamniotic IL-1α causes an acute detrimental inflammatory response inthe ileum, suggesting that induction of IL-1 is a critical element in thepathophysiological effects of endotoxin induced chorioamnionitis." (PMID 21479249, 2011). "Additionally, placental tissues from chorioamnionitis-affected deliveries presented with a seventeen-fold increase in IL-1 abundance compared to healthy pregnancies, with a predisposition towards greater placental IL-1β compared to IL-1α." (PMID 36994431, 2023). "C57BL/6 infected animals predominantly exhibited mild to moderate chorioamnionitis (P<0.0001), and a significant reduction in placental expression of IL-1α, IL-1β, IL-6, TNF-α, S100A8, and S100A9 compared to sham controls (P<0.02)." (PMID 22952869, 2012). "Disease outcome was assessed by microbial culture, in situ detection of U. parvum in fetal and utero-placental tissues, grading of chorioamnionitis, and placental gene expression of IL-1α, IL-1β, IL-6, TNF-α, S100A8, and S100A9." (PMID 22952869, 2012). "Cases with histological chorioamnionitis also showed a marked increase in the expression of proinflammatory cytokines (IL-1α, TNF-α) and chemokine IL-8." (PMID 17064297, 2006). "Increased lung compliance and improved lung functionality are seen in fetal rabbit and lamb models of chorioamnionitis, as well as after intra-amniotic injection with IL-1α.In murine models, BPD is precipitated by a rise in pulmonary inflammation, and IL-1β plays a key role in its pathogenesis." (PMID 36994431, 2023). "We performed targeted analyses utilising Random Forest Algorithm of the same eight cfRNA targets (IL1α, IL1β, IL6, IL8, IL10, IL18, CD14, TNFα) used in the chorioamnionitis study." (PMID 40464837, 2025). "Conversely, severe protracted chorioamnionitis with cellular necrosis was the predominant lesion phenotype in BALB/c mice, which also exhibited a significant increase in placental expression of IL-1α, IL-1β, IL-6, TNF-α, S100A8, and S100A9 (P<0.01)." (PMID 22952869, 2012).
coronary artery disease (8 papers, 2013 to 2024). "Interleukin family was also predicted to be related to coronary artery disease, including IL 6, IL4, IL10, IL1A, and IL1B." (PMID 29861771, 2018). "Another pattern has been reported in the population with ischemic heart disease in Western Australia, where IL1B + 3954 T > C (rs1143634) SNPs were studied and TT homozygotes had larger waist circumference and the largest value was noted in individuals with two copies of the IL1A:IL1B T:T haplotype." (PMID 35139823, 2022). "CSF3, IL-1A, CCR7, IL-18, and MAPK14, as well as IL-17 signaling pathway and cytokine and cytokine receptor interaction signaling pathway related with inflammatory response might be the potential biomarker and targets for the treatment of coronary artery disease." (PMID 33777109, 2021). "Although many studies have shown the release of IL-1α and IL-1β on AMI experimental models, the increase in IL-1 plasma levels in AMI patients was not systematically highlighted, some studies showing values ​​comparable to those of patients without coronary disease." (PMID 34180324, 2021).
glioblastoma (8 papers, 2013 to 2025). The most malignant astrocytic tumor (WHO grade IV). "Cytokine profiling of the mesothelioma cell line suspension revealed significantly elevated production of G-CSF, GM-CSF, IL-8, CXCL1, and IL-1α compared to glioblastoma and acute myeloid leukemia cell lines." (PMID 39768223, 2024). "In contrast to the expected effects of ACA on cytokine levels, in the present study, an increased expression of IL-6 and IL-1α was observed in glioblastoma cells treated with ACA." (PMID 23833677, 2013). "It was shown that the glioblastoma cell lines CCF3 and U87-MG overexpressed IL-1α and 1β." (PMID 40727443, 2025). "We also noticed that the transcription of key genes involved in inflammation, proliferation, angiogenesis and extracellular matrix remodelling (including MMP2, HIF1A, IL1B, IL1A, IL1R1, MMP2, VEGFA), processes vital to glioblastoma development, were down-regulated by RND3 knock-down." (PMID 26132659, 2015). "Moreover, Kammerer and co-workers observed significant upregulation of inflammation-related genes, including CXCL2, CXCL3, IL1A, and IL6 receptor (IL6R)) after non-lethal 5-ALA-PDT in a panel of prostate and glioblastoma cell lines." (PMID 26705830, 2015).